S100B (S100 calcium binding protein B)
Diseases named in the same sentence as S100B in open-access papers (continued):
Sharing a sentence is not in itself a finding about the gene and the disease.
brain injury (continued). "Given the importance of S100B protein, accesses to facilities for its measurement, inhospitals managing brain trauma victims, seems to be necessary." (PMID 24396798, 2013). "Brain trauma damages glial cells, releasing large amountsof S100-β into the peripheral blood." (PMID 39801405, 2025). "In this context, the protein S100b is a promising circulating biomarker for the diagnosis of BD, as its detection in acute brain injuries, in neurocritical patients in emergency rooms and ICUs, has been employed in clinical practice for monitoring these patients in many countries." (PMID 39036258, 2024). "In pediatric traumatic brain injury, S100B levels correlated to the extent of brain injury." (PMID 39744107, 2024). "Recently, we hypothesized that concussion resolution at 36 h in professional rugby players may be related to an elevation in sRAGE, which may regulate blood levels of S100B and thus preserve brain function." (PMID 37047574, 2023). "Increased concentrations of S100B have been observed in various clinical conditions such as brain trauma and ischemia, which may be due to the destruction of astrocytes." (PMID 37759909, 2023). "In addition to growth factors such as brain-derived neurotrophic factor (BDNF) up-regulating neurogenesis, S100B contributes to hippocampal network repair after brain injury as well as memory consolidation during development." (PMID 36076994, 2022). "Moreover, Hol and Pekny have suggested that an early increase in glial markers such as S100B is a result of early glial cell activation, since glial activation is a common element in brain trauma and ischemia." (PMID 33917473, 2021). "The consequences of BBBdisruption involve the passage of neurotoxic substanceswhich interact with brain cells and cause brain injury.Specific proteins in the brain cells such as S100B andGFAP, are released into plasma or cerebrospinal fluid(CSF) during brain injury." (PMID 32779431, 2020). "Moreover, patients with S100B level ≥4 μg/L were usually accompanied by serious hemorrhagic brain injury, yet ones with S100B level <4 μg/L were prone to suffer from diffusive embolic cerebral infarction." (PMID 29568675, 2018). "In turn, increased expression and secretion of S100B from astrocytes may be reflected in the CSF patterns as reported in traumatic brain injury, AD and sCJD." (PMID 29126445, 2017). "A study of collegiate and semi-professional athletes who completed S100B testing at baseline and following concussion demonstrated that relative and absolute increase in serum S100B could accurately distinguish concussion from sport-related exertion." (PMID 27761129, 2016). "It has been estimated that adding the measurement of S100B to clinical decision tools for mild traumatic brain injury patients could potentially reduce the number of CT scans by 30%." (PMID 27468268, 2016). "This study focuses on the level of serum S100B after brain injury at the time of admission,48 hours and a week later, or when the patient is labeled as brain death, to predict outcomeof patients after traumatic brain injury." (PMID 24396798, 2013). "In this study we have shown that elevations of serum S100B indicating blood-brain barrier disruption occur in football players who experience sub-concussive head hits (SHH) below the threshold for a diagnosis of concussion." (PMID 23483891, 2013). "Many studies have shown the potential of S100B as a biomarker in brain injuries." (PMID 23830006, 2013). "S100B levels in biological fluids constitute a recognized clinical parameter to evaluate patients with acute brain injury, and a special emphasis has been recently placed on mild traumatic brain injury since S100B levels have been proposed as a reliable screening tool in this pathological condition." (PMID 37298554, 2023).
brain injury (continued). "Following some neurological insults, alarmin levels may even be utilized as clinical biomarkers; for instance, plasma levels of HMGB1 and S100B have been correlated with poor outcomes in patients with aneurysmal subarachnoid hemorrhage and traumatic brain injury." (PMID 34679362, 2021). "Furthermore, emerging data on salivary-based S100B, which has shown to adequately differentiate concussion patients from controls (AUC = 0.74), may have a direct implication to clinical practice in near future." (PMID 33096545, 2020). "Because the permeability of cell membrane and blood-brain barrier increased, S100-β can be released into the cerebrospinal fluid and the systemic circulation through the blood-brain barrier; thus, the detection of S100-β concentrations in peripheral blood can sensitively reflect brain injury." (PMID 29445737, 2017). "Thus, S100B autoantibodies may be useful biomarker after acute concussion and in evaluating more chronic consequences of head trauma." (PMID 27761129, 2016). "Therefore, we investigated whether measurement of S100B, a consolidated marker of brain injury, in salivary fluid of PA newborns may constitute a useful tool for the early detection of asphyxia-related brain injury." (PMID 25569796, 2015). "We measured S100B in the cerebrospinal fluid (CSF) and serum (Cobas e411 electrochemiluminescence assay, Roche) longitudinally in a large cohort of patients treated with a ventricular drainage following traumatic brain injury (TBI) or subarachnoid hemorrhage (SAH)." (PMID 20671945, 2010). "Although a generally linear relationship exists between serum S100B concentrations measured by ELISA and a commercially available kit, ELISA values tended to be higher than commercial kit measurements particularly at concentrations over 0.7 μg/L, which are suggestive of brain injury." (PMID 18803814, 2008). "Although a general linear relationship exists between serum S100B concentrations measured by ELISA and a commercially available kit, ELISA measurements tended to be higher than commercial kit measurements particularly in concentrations over 0.7 μg/L, which are suggestive of brain injury." (PMID 18803814, 2008). "The occurrence of post-traumaticmental disorder was taken as the dependent variable, while family satisfaction,the severity of traumatic brain injury, and serum levels of MMP-9,S100-β, and GFAP were included as independent variables." (PMID 39801405, 2025). "While CAMs regulate migration, the major PC5diagnosis marker, S100B, is an astrocyte-expressed protein indicating BBB disruption due to e.g. brain trauma and cerebrovascular diseases." (PMID 35856063, 2022). "Remote ischemic conditioning (RIC) reduced serum levels of S-100B and NSE 24 h after a severe brain injury when RIC was administered 1 h after hospital admission." (PMID 32737368, 2020). "Specific attention has focused onthe biomarkers lactate, S-100β, NSE and GFAp, which have all shown to be goodindicators correlating to injury magnitude in traumatic brain injury, as well asoutcomes and survival." (PMID 31454201, 2019). "S100B and NSE are used as biomarkers for neuronal damage and are directly related to disease progression in patients with acute brain injury." (PMID 31671515, 2019). "Several cytokines, glial proteins, and enzymes with elevated expressions, such as TGF-β1, S100B, GFAP and TG2, are highly suspected of being involved in traumatic brain injury (TBI), neuroinflammation and acute CT, and also in the pathogenesis of AD." (PMID 29273062, 2017). "S-100β has been identified as a biomarker of BBB disruption in neurodegenerative diseases and traumatic brain injury (TBI)." (PMID 29249869, 2017). "In addition to serum MMP-9, S100-β, and GFAP, other biomarkers likeneuron-specific enolase (NSE) are also elevated after traumatic brain injury,reflecting the extent of neuronal damage." (PMID 39801405, 2025).
brain injury (continued). "An increase in the frequency and magnitude of head impacts, without a concussion being detected, resulted in the largest acute changes in S100B plasma levels." (PMID 37047574, 2023). "In professional rugby players, a significant increase in S100B concentration was reported within 2 h following a game (without concussion), and this increase was correlated with the number of body collisions during a match." (PMID 37047574, 2023). "Therefore, we conducted this double-blind, placebo-controlled, randomized trial to assess the possible effects of early melatonin administration on the levels of biomarkers, including MDA, S100B, and C-reactive protein (CRP) in patients with brain injuries." (PMID 35517892, 2022). "It was observed that post-mortem serum S100B levels were also significantly elevated in fatalities with non-TBI-related brain injuries such as strangulation or hanging." (PMID 35226180, 2022). "Early prehospital and in-hospital S100B levels < 0.10 μg/L safely rules out traumatic intracranial lesions in adult patients with mild traumatic brain injury, but specificity is lower with early prehospital sampling than with in-hospital sampling." (PMID 34078435, 2021). "The authors also show that in the absence of concussions, S100B tends to return quickly to baseline after a game." (PMID 32098419, 2020). "Second, the analysis of 15 football players yielded that serum S100B levels were acutely increased after football games without a concussion." (PMID 31024425, 2019). "Sevoflurane pretreatment can activate TLR3 and TLR9 signaling pathway, upregulate TLR3 expression and TRIF expression, decrease TLR9 expression, and downregulate NF-κB expression and inhibited the production of S100β and IL-6, thereby lessening CPB inflammation-induced brain injury." (PMID 29445737, 2017). "A second problem for using S100B clinically is the observation that serum levels rise not only after concussion but also after a game in which no concussion was observed." (PMID 24416325, 2014). "In this study, S100B protein level was assessed as a biomarker to predict brain death inpatients with severe head trauma (GCS ≤ 8), and it was found that S100B proteinlevels increased in the brain death group, 48 hours after brain trauma." (PMID 24396798, 2013). "There have been recent reports that serum S100B levels are positively correlated with body mass index without evidence of traumatic brain injuries." (PMID 20844757, 2010). "On this light, FDA, EMA and more recently NIH approved the inclusion of NB such as S100B, Ubiquitin carboxyl-terminal hydrolase L1a and glial fibrillary acidic protein (G-FAP) in clinical protocols of adult and pediatric diseases such as traumatic brain injury." (PMID 35643585, 2022). "However, the subgroup analysis showed a significant reduction in S100B in patients with non-traumatic brain injuries, receiving melatonin versus placebo (p: 0.016)." (PMID 35517892, 2022). "In conclusion, this study shows that the repetitive head trauma occurring in olympic boxing may induce changes in CSF NFL, GFAP, T-tau and S-100B, even without anamnestic or clinical symptoms of a concussion or traumatic brain injury." (PMID 22496755, 2012). "In addition, it is assessed whether S-100B concentrations differ between poly-traumatised patients with and without brain injury." (PMID 27031106, 2016). "In addition, it was assessed whether S-100B concentrations differ between poly-traumatised patients with and without brain injury." (PMID 27031106, 2016). "Though S-100B and NSE are not ideal candidates for monitoring biomarkers, they are consistently elevated after severe clinical brain injury." (PMID 32737368, 2020). "The extent and intensity of head impacts and serum values of S100B, UCH-L1, and beta-2 transferrin were measured pre- and post-game from 15 college football players who did not experience a concussion after a game." (PMID 24806476, 2014).
depression (72 papers, 2008 to 2026). "Serum S100B has been proposed as a peripheral biomarker associated with neuroinflammatory and astroglial stress-related processes in major depressive disorder (MDD)." (PMID 42278267, 2026). "The results showed that the SHAP value for S100β was 0.330, indicating that an increase in S100β significantly raised the risk of depression." (PMID 40589656, 2025). "In this study, we employed machine learning methods to identify the most important risk factors for depression, with S100β and NSE emerging as key indicators." (PMID 40589656, 2025). "Venlafaxine reduced hippocampal S100b expression and reversed depressive-like behavior suggesting that high levels of S100b predict the risk for depression and antidepressant response." (PMID 37252156, 2023). "Actually, mice with extra copies of S100β are more sensitive to this housing, which has been linked to human major depression." (PMID 36407114, 2022). "A well-known example is SOD1 related to neuroinflammation, hyperthyroidism, hypertensive disease (associated also with GJA1), diabetes mellitus (associated also with IGF2BP2) and depressive disorders (associated also with S100B)." (PMID 34570756, 2021). "Serum S100B protein level in two groups of elderly patients with depression was detected by enzyme-linked immunosorbent assay before and after treatment." (PMID 30278520, 2018). "S100B, a glia derived protein, is linked to depression and has been suggested as a biomarker for depression outcomes in several populations." (PMID 30581620, 2018). "The aim of the present study was to study the association of serum S100B levels with antidepressant treatment response and depression severity in melancholically depressed inpatients." (PMID 26364276, 2015). "In conclusion, these findings strongly support the concept of serum S100B as a reliable and sensitive diagnostic biomarker for mood disorders and the clinical response to antidepressive treatment in unipolar major depressive disorder." (PMID 20585358, 2010). "S100B, a calcium-binding protein secreted by astrocytes, has been shown to be increased in serum of patients with depression and associated with good therapeutic response and clinical outcome." (PMID 21614209, 2010). "Hence, our findings point to a potential causal explanation behind previously reported S100B associations with brain disorders, possibly opening avenues for novel treatments of major depression and bipolar disorders." (PMID 37225692, 2023). "Adipose tissue contains S100B, which predisposes obese patients to depression." (PMID 37252156, 2023). "Our systematic review aims to compare results on circulating S100B levels in five major psychiatric disorders with shared genetic susceptibility: schizophrenia, bipolar disorder, major depressive disorder, attention-deficit/hyperactivity disorder, and autistic spectrum disorder." (PMID 37759935, 2023). "Elevated concentrations of S100B in serum samples have been associated with major depression, and a decrease in S100B in the course of therapy may be an indicator of therapy response, although the latter is under dispute." (PMID 34021122, 2021). "We evaluated mature BDNF (mBDNF), S100B levels in plasma and their associations with depression severity in 30 Selective Serotonin Reuptake Inhibitor (SSRI)-resistant MDD patients enrolled in a randomized controlled trial of ketamine compared (n = 20) to a placebo (n = 10) control (saline)." (PMID 34354565, 2021). "Cluster two also included the SOD1 gene but it also included other genes with high DPI such as GJA1, associated with cancer, hypertensive disease, heart anomalies and S100B, associated with schizophrenia, myocardial infarction, mental depression and bipolar disorders." (PMID 34570756, 2021). "Similarly, S100b is elevated in the plasma of major depression patients, and overexpression of S100 is associated with depressive-like behaviors observed with the forced swim test in mice." (PMID 31749681, 2019).
depression (continued). "In this study we examined for differences in serum S100B concentrations between subjects with and without depressive symptoms in a cohort of patients with T2DM and for potential associations between S100B serum levels and metabolic as well as depression parameters." (PMID 30581620, 2018). "We hypothesized that the anti-depressant activity of venlafaxine is associated with its effects on S100B mRNA level and protein expression in the hippocampus in a rat depression model induced by chronic unpredictable mild stress (CUMS)." (PMID 27931233, 2016). "Taken together, we speculate that chronic stress may lead to damage of astrocytes and the hippocampus, causing increases in S100B, which in turn may result in pro-inflammatory cytokines and depression-like symptoms in the CUMS model of depression." (PMID 27931233, 2016). "In sum, serum S100B may constitute a diagnostic, prognostic and treatment biomarker for major depression, schizophrenia and neurological diseases." (PMID 22916238, 2012). "It has been demonstrated that increased S100B serum concentrations in major depression were associated with good therapeutic response and clinical outcome, which suggests a role of S100B in the modulation of the course of depression." (PMID 21614209, 2010). "At the BBB, S100B and claudin-5 are the most enriched proteins, and their dysfunction has been implicated in neuroinflammatory disorders such as MS, neurodegenerative diseases such as Alzheimer’s, and psychiatric disorders including depression and schizophrenia." (PMID 32085663, 2020). "Elevated serum S100B levels have been reported in individuals with major depressive disorder (MDD), bipolar disorder, and anxiety, often correlating with disease severity, glial dysfunction, and increased blood–brain barrier permeability." (PMID 40728957, 2025). "SHAP analysis revealed that elevated levels of S100β (0.330), NSE (0.060), and PLT (0.031) significantly increased the risk of depression." (PMID 40589656, 2025). "Preclinical studies using animal models of depression have consistently shown a decrease in the number and expression of cells expressing S100B and GFAP, including in the hippocampal dentate gyrus (DG)." (PMID 38783266, 2024). "Our finding was the first to find a significantly altered s-100β protein in the two depression subgroups, providing a valuable biological marker to identify UD and BD." (PMID 40224600, 2023). "Several clinical studies reported that serum levels of S100B are correlated with depression severity and recurrence." (PMID 37252156, 2023). "Serum S100B was analyzed in 22 patients with depression who received repetitive transcranial magnetic stimulation (rTMS) for three weeks with ultra-high frequency stimulation (n = 14) or sham (n = 8)." (PMID 37759935, 2023). "The meta-analysis showed elevated levels of serum S100B in patients with affective disorders (depression and mania) compared with the control group." (PMID 37960185, 2023). "Cognitive Failures Questionnaire scores and severity of depression measured with MADRS were positively correlated with levels of S100B." (PMID 37759935, 2023). "A positive correlation with the severity of depression, persistent error number in the Wisconsin Cards Sorting Test, and baseline S100B serum levels were detected." (PMID 37759935, 2023). "A positive correlation of S100B concentration with family history of depression was discovered in adult and adolescent patients." (PMID 37759935, 2023). "The present review summarizes the findings on circulating S100B levels (serum or plasma) in five major psychiatric disorders: schizophrenia, major depressive disorder, bipolar disorder, autistic spectrum disorder, and attention-deficit/hyperactivity disorder." (PMID 37759935, 2023). "Overall, regulating S100B and glucose metabolism is likely to alleviate depression in patients with metabolic disorders." (PMID 37252156, 2023).